MMP9 (matrix metallopeptidase 9)
Diseases named in the same sentence as MMP9 in open-access papers (continued):
Sharing a sentence is not in itself a finding about the gene and the disease.
tumor (continued). "In this respect, up-regulation of MMP-9 expression in various types of human cancers contributes to tumor progression, invasion, and metastasis." (PMID 24778099, 2014). "Our results showed significant decrease of angiostatin and MMP-9 expression during 21 days of treatment when the tumor size was smallest in size." (PMID 25549350, 2014). "Most important, in situ zimography with an MMP-2 inhibitor for the first time demonstrated a strong impact of MMP-9 activity on the degree of tumor infiltration during PTC progression." (PMID 24778099, 2014). "In another report using a xenograft model in mice, treatment of carcinoma cells with the chemotherapeutic agent paclitaxel increased MMP-9 expression and tumor cell metastasis, and this was also blocked with an MMP-9 inhibitor." (PMID 24956101, 2014). "Neutrophil-derived MMP9 has been found to be important in models of skin and rip-Tag pancreatic cancers where they sustain tumor angiogenesis." (PMID 25072019, 2014). "The interaction of HMGB1 with RAGE leads to activation of the NF-κB, MAPK, and type IV collagenase (MMP-2/MMP-9) signaling pathways, all of which degrade extracellular matrix protein and play a major role in tumor invasion and metastasis." (PMID 25356587, 2014). "More intense immunostaining of fascin and MMP-9 was observed at the invasive fronts compared with other areas of the tumor." (PMID 24993803, 2014). "These vesicles were shown to contain bioactive matrix metalloproteinases (MMP2 and MMP9), enzymes that have critical importance in tumour invasion, in addition to RNA, ADP-ribosylation factor 6 and caveolin-1." (PMID 24931391, 2014). "It is worth noting that MMP-9 has been identified as being overexpressed in BALB-neuT mammary cancer which would seem to point to its important role during tumor progression." (PMID 25136593, 2014). "Our results extend these findings by demonstrating that there is not only more pro-active (latent) and active MMP-9 in PTC than in adjacent non-tumor tissue, but that the ratio of active to total MMP-9 is significantly elevated in PTC." (PMID 24778099, 2014). "In a similar study using a mouse glioblastoma tumor model, MMP9-producing macrophages and TIE2+ monocytes (TEM) contributed to the release of bioactive VEGF-A from its ECM-bound form." (PMID 24634660, 2014). "The study found that in the tumor tissues, MMP-9 and TIMP-1 were significantly higher than in the normal counterparts." (PMID 24520285, 2014). "MMP-2 and MMP-9 immunoexpression in tumor cells was cytoplasmic, finely granular, and varied in intensity and percentage." (PMID 25097794, 2014). "In the current research more intense expression of fascin and MMP-9 was observed at the invasive fronts compared with other areas of tumor." (PMID 24993803, 2014). "The most significant up-regulated genes identified in this tumor model are related to chromosome-end replication (Tert), invasion and metastasis (Plau, Serpine1, Mmp9 and Mmp1), cell adhesion (Itgb3 and Itgav) and angiogenesis (Angpt1 and Vegfa)." (PMID 24928374, 2014). "Gelatinase B/MMP-9, therefore, exhibits an integral relationship with tumour-associated inflammation." (PMID 24473089, 2014). "The serum level of MMP2 and MMP9 were both up-regulated under MT treatment under the mechanical damage indicated the highly migration ability of tumor cells while MMP13 also showed the enhanced trend." (PMID 24804772, 2014). "MMP9 also known as gelatinase B is expressed by active osteoclasts and giant tumors and plays an important role in resorption and tumor growth in the the bone micro-environment." (PMID 25010555, 2014). "Activation of TIMP-1 free gelatinase B/MMP-9 releases angiogenic factors stored within the extracellular matrix, which promote endothelial sprouting and new vessel formation, and gelatinase B/MMP-9-assisted tumour cell intravasation and dissemination." (PMID 24473089, 2014).
tumor (continued). "In our data, suppression of MMP-9 would contribute to accompany hypo-angiogenesis in the tumor stromal component in fat-1 tumor." (PMID 24586907, 2014). "In tumor tissue, expression of MMP-9 and bombesin was observed in almost the same population of cancer cells and was associated with high grade tumors." (PMID 24978435, 2014). "We found that most of matrix metalloproteinases (MMPs), especially MMP2 and MMP9, is down-regulated in cancer tissues compared to non-tumor tissue." (PMID 24622401, 2014). "In our in vivo model, the impact of MMP9 knockdown in tumor cells on spontaneous metastasis was striking, resulting in a complete blockade of pulmonary metastasis." (PMID 24811362, 2014). "Function: Like MMP-2, MMP-9 derived from both tumor cells and tumor microenvironment plays important roles in the process of cancer metastasis." (PMID 24978435, 2014). "Elevated PLD is associated with MMP9 release in an MAPK/NFKβ-dependent pathway in an acidic environment, which mimics the tumor microenvironment." (PMID 24103483, 2014). "Studies that evaluated the prognostic value of stromal MMP9 found significant associations with shorter recurrence-free survival, while the prognostic interpretation of tumor cell MMP9 has remained more ambiguous." (PMID 24811362, 2014). "Since MMP1, MMP3 and MMP9 were involved in tumor invasion and metastasis and can be regulated by NF-κB pathway, we further investigated the effect of RANKL on the MMPs." (PMID 25268581, 2014). "Among MMPs, MMP-2 and MMP-9 are regarded as the critical indicators for tumor cell invasion and metastasis." (PMID 24797571, 2014). "We therefore measured the effects of embelin on the expression of E-cadherin, Snail, Slug, ZEB1, MMP-2 and MMP-9 in tumor tissues." (PMID 24694877, 2014). "Bisphosphonates, which are routinely prescribed for cancer patients with bone metastasis, have also been demonstrated to decrease MDSC expansion in tumor-bearing mice through the reduction of MMP-9 expression." (PMID 25054153, 2014). "We found that while expression of MMP-2 and MMP-9 was reduced in Spn4A-expressing tumor cells, mRNA expression levels of TIMP-1 and TIMP-2 was significantly increased." (PMID 24961901, 2014). "Treatment of AsPC-1 xenografted mice with embelin induced the expression of E-cadherin and inhibited the expression of MMP-2, MMP-9, Snail, Slug, and Zeb-1 in tumor tissues compared to untreated control group." (PMID 24694877, 2014). "Treatment with 3 mg/kg IMD-0560 failed to reduce the number of MMP-9-expressing tumor cells, but 5 mg/kg IMD-0560 greatly reduced the number of MMP-9-expressing tumor cells." (PMID 25373602, 2014). "By the end of the study, the basal MMP-9 plasma levels in the tumor-free mice were approximately 11.3 ng/mL." (PMID 24960186, 2014). "In tumor-bearing state, G-CSF and IL-6 cooperated to enhance the potential of neutrophils to express Bv8 and MMP-9, and decrease the ability of neutrophils to release TRAIL, MPO and NE." (PMID 25587026, 2014). "In summary, DLL4/Notch/Hey1/MMP9 cascade mediates a direct interplay between endothelial cells and tumor cells, which eventually promotes RCC hematogenous metastasis." (PMID 24931473, 2014). "Tumors of K14-HPV16 mice in a null MMP9 background were found to be more aggressive, indicating that MMP9 inhibits certain aspects of tumor progression." (PMID 24658161, 2014). "Collectively, these studies suggest that ALK and the ALKF1174L mutation contribute to tumor vasculogenesis and pericyte recruitment via the regulation of VEGF and MMP-9, leading to a dense vascular network with smaller, more stable vessels." (PMID 24667968, 2014). "It was also assumed that the remaining activity was predominantly due to MMP-9, which increased gradually in tumors with a greater degree of tumor infiltration (b3 and c3)." (PMID 24778099, 2014). "MMPs especially MMP-9 and -2 are reported to be involved in tumor angiogenesis mainly through their degradative capacity." (PMID 24932681, 2014).
tumor (continued). "The mean MMP-9 expression was 142.1780 (SD 51.0358) in the main tumor mass and 171.0924 (SD 61.9203) at the positive margin of resection." (PMID 25097794, 2014). "Src inhibitors have shown promise in targeting MDSCs by inhibiting their recruitment and MMP-9 gene expression in the tumor microenvironment." (PMID 25054153, 2014). "Dysregulation of β-catenin and other Wnt components leads to activation of Wnt target genes, including c-myc, cyclin D1, and MMP-9, and the enhancement of tumor formation." (PMID 25471741, 2014). "In this review, we relate current concepts concerning the many ways in which gelatinase B/MMP-9 influences tumour biology." (PMID 24473089, 2014). "MMP-2 and MMP-9 metalloproteinases, our research subjects, have been reported as essential in the tumor dissemination and progression process by many authors." (PMID 24737953, 2014). "Most important, in situ zymography with an MMP-2 inhibitor for the first time demonstrated a strong impact of MMP-9 activity on the degree of tumor infiltration during PTC progression." (PMID 24778099, 2014). "Wnt3a expression in the primary tumor was significantly correlated with lymph node involvement (p = 0.038) and MMP-9 expression in primary, adjacent mesenchyme and metastatic sites (p = 0.038, 0.022 and 0.004, respectively)." (PMID 24564183, 2014). "Immunohistochemical study demonstrated immunoreactivity for MMP-9 in the tumor stromal fibroblasts was diffusely positive in wild type whereas focal in fat-1 mice." (PMID 24586907, 2014). "MMP9 is over expressed in many human cancers, and plays a critical role in tumor cell invasion, tumor growth, and angiogenesis by proteolytic degradation of extracellular components." (PMID 24810959, 2014). "In another study, reductions in MMP-9 levels by pharmacological methods in either wild-type or α1-knockout mice resulted in reduced angiostatin levels and increased tumor growth and vascularization." (PMID 25233229, 2014). "It has been previously shown that MMP9 is upregulated in tumor metastases and HSPB1 secretion is increased in tumorigenesis." (PMID 24465581, 2014). "We are currently studying the effects of HSPB1 glycosylation, phosphorylation and dimerization on MMP9-induced HSPB1 cleavage during tumor progression." (PMID 24465581, 2014). "Accordingly, Tie2+MMP9+ monocytic cells were consistently detected in the invasive tumor edge upon anti-VEGF therapies." (PMID 24809734, 2014). "Among matrix metalloproteases (MMPs), a family of zinc dependent endopeptidases, MMP-2 and MMP-9 have been considered to be critical for tumor growth, invasion and metastasis." (PMID 24885308, 2014). "HGF activation of tumour cell c-met induces gelatinase B/MMP-9 expression, increasing tumor cell motility and scattering." (PMID 24473089, 2014). "In the current study, a significant association was observed between the tumor size and the levels of VEGF and MMP-9, with levels increasing in parallel with tumor size." (PMID 24944618, 2014). "It has been shown that MMP9 is secreted by tumor cells as well as by cells residing in stromal compartments." (PMID 24658161, 2014). "The consumption of CAPE or CAPPE, however, significantly decreased the MMP-9 plasma level in these tumor-bearing mice." (PMID 24960186, 2014). "A previous study demonstrated that MMP-9 can accelerate tumor metastasis by promoting neovascularization and lymphangiogenesis." (PMID 24944618, 2014). "There was a significant correlation between MMP-9 expression and lymph node metastases (p = 0.002), advanced tumor stage (p = 0.005) as well as both estrogen receptor negative (p = 0.005) and progesterone receptor negative (p = 0.003) hormonal status." (PMID 24993803, 2014). "MMP9 is a key regulator of tumor angiogenesis by virtue of its contribution to post-translational regulation of VEGF expression and bioavailability." (PMID 24810959, 2014).
tumor (continued). "Gelatin zymography revealed a correlation between the MMP-9 activation ratio and nodal involvement, extrathyroid invasion, and the degree of tumor infiltration." (PMID 24778099, 2014). "Although it is well documented that MMP9 is required for tumor progression, the source of MMP9 is still a subject of discussion." (PMID 24658161, 2014). "It was proven that matrix metalloproteinase MMP2 and MMP9 degraded the basement membrane was a crucial step that promote tumor invasion and metastasis in many types of tumors." (PMID 24876827, 2014). "Taken together, these results indicate that oncologic outcomes are worse in patients whose tumors express high levels of CTHRC1, which promotes invasivity of tumor cell via ERK-dependent induction of MMP9 expression." (PMID 24504172, 2014). "MMP-2 and MMP-9, the most extensively studied MMPs in tumor invasion, mainly degrade collagen IV and a number of other ECM proteins." (PMID 25026293, 2014). "Knockout of MMP-9 leads to reduced skin and pancreatic carcinogenesis and metastasis showing delayed tumor vascularization." (PMID 24465581, 2014). "In cancer, MMP-9 (gelatinase B, 92 kDa) is thought to play a major role in tumor growth, angiogenesis, and metastasis." (PMID 24724091, 2014). "Next, the intensities of immunohistochemical staining of fascin and MMP-9 were compared in the invasive front versus other areas in each tumor." (PMID 24993803, 2014). "MMP inhibitors reduce angiogenesis, tumor number, and tumor growth, as does genetic ablation of MMP-9." (PMID 24586907, 2014). "The catalytically inactive MMP-9 was preferentially used over the wild-type enzyme because the enzyme activity of the wild-type MMP-9 is known to play a role in tumor cell invasion and deemed unsuitable for antifibrotic therapy." (PMID 25380300, 2014). "Increased MMP-9 levels and significant correlations between tumour stage and both BAL fluid and plasma MMP9 levels have been demonstrated in patients with NSCLC." (PMID 26316944, 2014). "EMMPRIN proteins have been well documented to stimulate the synthesis of MMPs such as MMP-1, MMP-2, MMP-3, and MMP-9 in fibroblast and tumor cells." (PMID 24705283, 2014). "Noteworthy, MDSCs have a direct function in promoting tumor angiogenesis through releasing soluble factors, such as MMP9 and VEGF, and experimental data from mouse models suggest that they are also able to differentiate into ECs." (PMID 25072019, 2014). "In treated mice, staining revealed MMP9+ cells at the tumor edge and peripheral invasive tumor nodules with rod or amoeboid shapes characteristic of “activated” microglia/macrophages, which were barely observed in control animals." (PMID 24809734, 2014). "MMP-9 is critical in the invasion and metastasis of tumors and is also considered as a type of tumor angiogenic factor involved in the signaling system of VEGF-VEGF receptor." (PMID 24396477, 2014). "MMP9 degrades type I collagen under certain conditions, allowing tumor cells to break from the site of the primary tumor, leading to invasion and metastasis." (PMID 24504172, 2014). "In the present study, we showed for the first time that Gen suppresses TPA-induced cell invasive activity and MMP-9 expression by reducing tumor migration and invasion of HCC." (PMID 24433534, 2014). "To confirm HSPB1 cleavage by MMP9 during tumor progression, we generated B6F10 cell lines secreting wild-type HSPB1 (consisting of a Flag-tagged N-terminus and a Myc-tagged C-terminus)." (PMID 24465581, 2014). "In fact, its oncogenic effect is related to the complex NGAL/MMP-9; while its anti-tumor effect is related to the inhibition of the pro-neoplastic factor HIF-1a, the HIF-1a-dependent VEGF and FAK." (PMID 24742531, 2014). "Growing evidence indicates that inflammatory cells, including monocytes/macrophages and neutrophils, constitute a major cellular source of the proangiogenic MMP-9 and contribute to tumor angiogenesis." (PMID 24392031, 2013).
tumor (continued). "This implies that irregular, asymmetric apoptosis and/or necrosis in tandem with MMP-9 expression create conduits and channels through which viable tumor cells can escape." (PMID 23175106, 2013). "Matrix metalloproteinase-9 (MMP-9) production by tumor and stromal cells is one of the most important factors for metastatic behavior of tumor cells." (PMID 23407024, 2013). "Scorbutic group tumors showed a pattern of apoptotic cells directly adjacent to MMP-9 staining, with necrotic areas forming patterns of breaches/conduits in the tumor from the core to the surface of the tumor." (PMID 23175106, 2013). "Early research showed that MMP-9 had a distinct role in tumor angiogenesis, mainly through its ability to regulate the bioavailability of vascular endothelial growth factor (VEGF)." (PMID 23941575, 2013). "MMP-9 is a collagenase responsible for digesting the extracellular matrix, which is a critical process for migration, invasion, and tumour growth in vivo." (PMID 23914254, 2013). "Some reports have showed that ATLL cells produce MMP-9, and that expression levels of MMP-9 are related to organ involvement and tumor progression." (PMID 24236041, 2013). "RNAi inhibition of MMP-9 and the protease cathepsin B dramatically reduced tumor pathogenicity of gliomas both in vitro and in vivo." (PMID 24198789, 2013). "Both peptide sequences were in turn linked by an octapeptide, cleavable by the MMP-2 (gelatinase A) and MMP-9 (gelatinase B) enzymes which are over expressed in tumor tissues, allowing the release of buforin IIb." (PMID 24101917, 2013). "Neutrophils can promote tumor growth by secretion of matrix metalloproteinase (MMP)-9 that prevents tumor cell apoptosis in the lungs and can promote tumor angiogenesis and neovascularization." (PMID 23508552, 2013). "Taken together, these in vitro results suggest that astrocyte secreted MMP-2 and MMP-9 proteins partially mediate tumor cell invasion." (PMID 24324647, 2013). "VEGF and MMP-9 are essential for tumor angiogenesis, and can be induced by a myriad of mediators found in tumor microenvironment, including hypoxia, TNFα or EMMPRIN." (PMID 23874303, 2013). "Increased expression of uPA, PAI-1, and MMP-9 reported in cancer has been related to poor tumour differentiation, invasive stage of cancer, poor patient prognosis, metastasis to secondary organs, and shorter survival time." (PMID 23766912, 2013). "For example genistein inhibited cell invasion reducing expression of MMP2 and MMP9 in human prostate epithelial and metastatic cells where tumor progression is positively correlated with the expression of MMP." (PMID 23554959, 2013). "Among these genes IL-8, PTHrP, TGF-β, and RANKL are extensively described for their role in bone biology whereas PTHrP, TGF-β, and MMP-9 are characterized for their involvement in tumor progression and skeletal metastasis." (PMID 24403228, 2013). "Several studies have demonstrated that MMP-2 and MMP-9 are critical for tumor invasion and metastasis by degrading collagen IV, a main component of basement membranes." (PMID 23877152, 2013). "Significant correlations were only found in high level of CypA and MMP9 expression with tumor differentiation and lymph node status." (PMID 24351116, 2013). "IHC analysis demonstrated the presence of MMP-9 in the tumor epithelium, including areas highly populated with stromal fibroblasts." (PMID 23407024, 2013). "The level of PN1 itself is negatively regulated by matrix metalloproteinase 9 (MMP9), which is frequently up-regulated in human malignancies and associated with tumor progression, invasion and metastasis." (PMID 23880852, 2013). "Upregulation of secreted MMP9 correlated with an increase in tumor growth and angiogenesis compared to cells expressing low MMP9 levels." (PMID 24216994, 2013).